FER (FER tyrosine kinase)
Diseases named in the same sentence as FER in open-access papers (continued):
Sharing a sentence is not in itself a finding about the gene and the disease.
cancer (24 papers, 2013 to 2026). A tumor composed of atypical neoplastic, often pleomorphic cells that invade other tissues. "The MAN2A1-FER fusion facilitates the transport of the FER kinase to the Golgi apparatus, where it activates and promotes cancer through the epidermal growth factor receptor (EGFR) signaling pathway." (PMID 39963268, 2025). "We first compared epigenetic changes accompanying BORIS’s binding to the intronic sites of GAL3ST1 and FER genes in cancer cells to that in BORIS-negative cells." (PMID 38297316, 2024). "In this study, we showed that both GAL3ST1 and FER testis-specific transcripts are abnormally activated in cancer cells, coinciding with aberrant BORIS expression and its binding to the intronic promoters." (PMID 38297316, 2024). "Among retinoids, FeR has been regarded for long as a promising antitumor agent due to its ability to induce cancer cell differentiation, death, and growth arrest." (PMID 39497135, 2024). "FeR is a derivative of retinoic acid, able to induce cancer cell differentiation, growth arrest and death, through a multi-branched action on different molecular pathways linked to cell cycle, proliferation, apoptosis and stem cell dormancy." (PMID 39497135, 2024). "Overexpression of FER has been identified in several cancer types, and FER has been shown to activate MAP kinase signaling by phosphorylating receptor tyrosine kinases including EGFR and MET." (PMID 35706047, 2022). "Feline sarcoma-related protein (FER) is known to play a critical regulatory role in several carcinomas." (PMID 34295819, 2021). "In this study, we showed that overexpression of FER in Drosophila wing disc resulted in cell migration, a key step in the progression of cancer." (PMID 31264309, 2019). "Since FER regulates the recycling of ECM-dependent adhesion complexes in cancer, it indicated that FER may also control GFR activation during invasive growth." (PMID 41115375, 2025). "Therefore, the direct binding of BORIS to intronic regions concurrently bound by CTCF in FER and GAL3ST1 genes appears to be associated with transforming these CTCF sites into active internal promoters, thereby driving alternative cancer-testis-specific transcriptional start sites." (PMID 38297316, 2024). "The Fps/Fes-related tyrosine kinase (FER) gene encodes a non-receptor tyrosine kinase involved in the regulation of cell migration, cell cycle progression, cell adhesion, and signal transduction pathways that may be implicated in cancer development." (PMID 39123689, 2024). "The receptor tyrosine kinase FER activates MAP kinase pathway signaling and regulates cell adhesion in cancer cells." (PMID 35706047, 2022). "YY1 was shown to bind to Feline sarcoma-related (FER) promoter and repress its expression; where FER has been shown to induce the phosphorylation of STAT3, which in turn enhances the expression of MMP2 and cancer progression." (PMID 31824839, 2019). "Our study reveals FER as a positive regulator of JNK‐mediated cell migration and suggests its potential role as a therapeutic target for cancer metastasis." (PMID 31264309, 2019). "In conclusion, our work provides new insights into the roles of FER in regulating cell migration and JNK signalling and reveals a potential novel therapeutic target for cancer metastasis." (PMID 31264309, 2019). "Many of the identified peptide substrates, such as the FER/FES kinases, are involved in one specific task such as cell adhesion, an important process in cancer metastasis." (PMID 28978141, 2017). "Studies in several cancer types have identified feline sarcoma-related protein (FER), a ubiquitously expressed non-receptor tyrosine kinase, as a mediator of proliferation, cell-cell adhesion, cytoskeleton dynamics and migration." (PMID 41115375, 2025).
cancer (continued). "Furthermore, these transcription factors are enriched in cancer-related kinases such as lymphocyte-specific protein tyrosine kinase (LCK), LYN proto-oncogene (LYN), spleen tyrosine kinase (SYK), Janus kinase 3 (JAK3), and FER tyrosine kinase (FER)." (PMID 40612864, 2025). "In addition, overexpressed FER could phosphorylate EGF receptor and activate the EGF-mediated NF-κB signaling pathway, which is crucial for cancer cell survival and proliferation." (PMID 23420638, 2013).
tumor (13 papers, 2009 to 2025). "Compared with the mice injected with CAOV4shCon cells, the pharmacological degradation of FER kinase or the genetical knockdown of FER expression showed an equivalent decrease in tumor nodules on the peritoneal wall." (PMID 37196766, 2023). "Downregulation of FER substantially inhibits tumor cell migration, invasion, and metastasis, indicating the urgent need and market potential for developing antagonists against FER kinase to benefit ovarian cancer patients." (PMID 37196766, 2023). "To evaluate alterations in tumor growth and formation of metastatic lesions resulting from FER downregulation, we used a mouse xenograft model." (PMID 30909648, 2019). "Further immunohistochemical analysis in 87 paired samples of ccRCCs and ADTs confirmed overexpression of FER protein in tumor tissue." (PMID 23420638, 2013). "The mechanisms involved in FER regulation of tumorigenesis likely differ depending on tumor type." (PMID 30909648, 2019). "Thus, although FER appears to be a critical pro-metastatic factor in various neoplasms, targeted approaches to interfere with these properties would need to take into account the identity of downstream pathways activated in individual tumor types." (PMID 30909648, 2019). "In addition, FER protein expression in 206 ccRCC samples was significantly correlated with tumor size, T stage, N classification, metastasis, recurrence and Fuhrman grade, while associations with age and gender were not identifed." (PMID 23420638, 2013). "Nevertheless, FER was identified as a Src substrate and is involved in tumor transformation." (PMID 19835603, 2009). "This analysis revealed a virtual absence of FER gene mutations in this tumor type." (PMID 30909648, 2019). "GGA2, FER and STXBP2: Exhibit varied expression patterns, with some showing significant differences between tumour and normal tissues." (PMID 41362116, 2025). "We also assessed the consequences of FER downregulation on formation of metastatic foci, using BLI to monitor tumor-bearing mice longitudinally." (PMID 30909648, 2019). "Our analysis also showed consistent FER expression and transcript abundance in all samples reported, irrespective of the tumor grade, with higher mRNA levels detected in a small subset of these tumors." (PMID 30909648, 2019). "Using patient-derived tumor organoid (PDO) models of invasive HNSCC, we demonstrate that FER, a non-receptor tyrosine kinase that correlates with poor survival in HNSCC patients, is essential for growth factor receptor dependent invasive growth in Collagen-I extracellular matrix (ECM) networks." (PMID 41115375, 2025).
infection (1 paper, 2022). The state of being infected such as from the introduction of a foreign agent such as serum, vaccine, antigenic substance or organism. "PR proteins, which are downstream of FER genes, can induce plant programmed cell death, which inhibits the spread of infection." (PMID 35596601, 2022).
FER also shares sentences with these, for which no sentence is quoted: acute myeloid leukemia (16 papers); liver cancer (6); acute promyelocytic leukemia (3); leukemia (3); acute respiratory distress syndrome (1); B-cell lymphoma (1); babesiosis (1); brain tumors (1); diabetes (1); diffuse large B-cell lymphoma (1); epilepsy (1); esophageal cancer (1); glioblastoma multiforme (1); Hepatic steatosis (1); Hypertension (1); hyperthyroidism (1); Insulin resistance (1); Intellectual disability (1); invasive carcinoma (1); lymphoma (1); malignant brain tumors (1); meningioma (1); microphthalmia (1); mucosal (1); Multiple Myeloma (1); myeloid leukemia (1); Obesity (1); peripheral T-cell lymphomas (1); renal cell carcinoma (1); schwannoma (1).
A further 5 diseases each share a sentence with FER in 1 paper.